OGT (O-linked N-acetylglucosamine (GlcNAc) transferase)
Diseases named in the same sentence as OGT in open-access papers (continued):
Sharing a sentence is not in itself a finding about the gene and the disease.
tumor (continued). "Similarly, OGT has been shown to play an important role in tumor progression and metastasis." (PMID 30515357, 2018). "Additionally, OGT depletion suppresses tumour growth in nude mice." (PMID 29435130, 2018). "Interestingly, the protein RBL-2, which is a key regulator of entry into cell division and may function as a tumor suppressor, was identified as a substrate for three isoforms of OGT." (PMID 26960196, 2016). "Collectively, these data indicate that the interplay between OGT and OGA activities finely tunes autophagic flux in a tumour microenvironment‐dependent manner." (PMID 41540817, 2026). "In colorectal adenocarcinoma (COAD), OGT collaborates with the deubiquitinating enzyme USP18 to inhibit STAT2 degradation, promoting M2 polarization of TAMs and supporting tumor immune evasion and growth." (PMID 41394960, 2025). "Rescue experiments confirmed that OGT overexpression reversed the anti-tumor effects of USP8 knockdown, solidifying the USP8–OGT axis as a core driver of iCCA." (PMID 41301681, 2025). "Inhibition of OGT with OSMI1 significantly reduces CSC populations and suppresses xenograft tumor formation, underscoring the necessity of O‐GlcNAcylation in this process." (PMID 41394960, 2025). "For example, in colorectal cancer, elevated OGT expression in metastatic lymph nodes enhances EZH2 stability via O-GlcNAcylation, thereby promoting tumor cell invasion and migration." (PMID 40852041, 2025). "Enzyme-directed medicines (e.g., OGT or PAD4 inhibitors) can also have effects on-target and off-tumor because these enzymes help normal tissue work." (PMID 41228299, 2025). "Both Retatrutide and the OGT inhibitor OSMI‐1 sensitized tumor cells to gemcitabine‐induced growth inhibition, resulting in marked suppression of tumor progression." (PMID 39868848, 2025). "In lipid metabolism, FASN is highly expressed in CRC and positively regulates the expression of OGT and GFPT1, further elevating O‐GlcNAcylation levels and forming a positive feedback loop that accelerates tumor growth and metastasis." (PMID 41394960, 2025). "We next investigated functional interplay of OGT and FOXC1 in asparagine/alanine biogenesis essential for ferroptosis repression and tumor progression." (PMID 40416363, 2025). "shRNA-mediated downregulation of GFPT1 and OGT inhibits cellular proliferation and the level of protein O-GlcNAcylation in vitro, and knockdown of GFPT1 leads to a significant decrease in tumor growth and metastasis in vivo." (PMID 38732103, 2024). "An OGT inhibitor, OSMI-1, can significantly inhibited NE differentiated PCa cell proliferation in vitro and tumor growth in vivo." (PMID 39505875, 2024). "Therefore, targeting OGT may be advantageous in inducing tumor cell apoptosis." (PMID 39285476, 2024). "In summary, our results identify OGT-mediated genomic stability and activate cGAS-STING pathway as an important tumor cell-intrinsic mechanism to repress antitumor immunity." (PMID 38168435, 2024). "Combined OGT inhibitor with anti-PD-L1 antibody markedly suppressed tumor growth and increased CD8+ T cells and production of IFN-γ and TNF-α in tumor." (PMID 38168435, 2024). "A number of small molecule compounds targeting OGT activity or OGT-mediated O-GlcNAcylation have been produced, such as OSMI-1 and OSMI-4, and have been widely used in tumor research." (PMID 39285476, 2024). "More importantly, our data revealed that OGT was critical for KIF1A induced NE differentiation and aggressive tumor growth." (PMID 39505875, 2024). "In line with this, OGT knockout not only dramatically abrogated the self-renewal and tumorigenic capacities of ALDH+ esophageal CSCs, but also suppressed the tumor-initiating potential of the PC cell line S2VP10 in vivo." (PMID 37298124, 2023). "OGT was deleted using the AAV8 system 5 months after DEN injection, and 2 months were allowed for tumor promotion." (PMID 37930118, 2023).
tumor (continued). "Besides, previous studies have demonstrated that OGT may contribute to the tumorigenesis of several malignancies, and it has been reported that elevated O-GlcNAcylation and OGT expression were involved in the facilitating of tumor growth and metastasis in HCC." (PMID 37559097, 2023). "In our present study, using a dataset obtained from the Clinical Proteomic Tumor Analysis Consortium (CPTAC), we found that OGT and p65 protein levels are indeed positively correlated." (PMID 37835439, 2023). "We observed between 2-and 6-fold increased basal expression of OGT in the three TNBC lines in our panel, which in all cases revealed upregulated OGT levels compared to the non-tumor line MCF 10 A." (PMID 37231419, 2023). "Correspondingly, our findings are the first to reveal that EIF3H inhibits ferroptosis by interacting with OGT, thereby accelerating HCC cell growth and tumor progression." (PMID 37559097, 2023). "Reinforcing these in vitro results, our models of TNBC tumors in DIO mice show elevated OGT levels, O-GlcNAc levels, and supported our published pathway whereby DIO mice display higher TNBC tumor initiation events than their lean littermates." (PMID 37231419, 2023). "Triptolide, a diterpene epoxide from the Chinese plant Tripterygium wilfordii, targets OGT, resulting in downregulation of heat shock factor 1 (HSF1) and other heat shock proteins (HSPs), ultimately leading to tumor cell death." (PMID 36104770, 2022). "The abundance of O-GlcNAc was elevated in HCC compared with the corresponding non-tumor sample; meanwhile, a significant reduction in OGA and unchanged OGT were detected in HCC." (PMID 34298689, 2021). "Conclusively, our study has presented functional experiments demonstrating that miR-181d regulated the OGT/KEAP1/NRF2 axis to promote the DDP resistance in vitro and tumor growth in vivo of OC." (PMID 34876558, 2021). "In order to confirm the physiological function of miR-181d/OGT/KEAP1/NRF2, A2780 cell-implanted xenograft tumor models were established to clarify the effect of OGT on tumor formation in mice." (PMID 34876558, 2021). "Pol ι was shown to stimulate Erk signaling to enhance OGT expression, and the G6PD inhibitor polydatin attenuated Pol ι induced tumor growth in vitro and in vivo." (PMID 34354953, 2021). "Recent evidence suggested that OGT promotes O-GlcNAcylation of G6PD, and this process is critical for G6PD activation and tumor progression." (PMID 34354953, 2021). "Mechanistically, changed OGT level regulated HIF-1α proteasomal-dependent degradation, the interaction between HIF-1α and pVHL, ER stress-mediated tumor cell survival, and cell metabolism." (PMID 34924561, 2021). "The pharmacological or genetic inhibition of OGT induces a potent reduction of mammosphere formation, as well as CD44H/CD24L, ALDH+, and NANOG+ tumor-initiating cell populations in breast cancer cells." (PMID 33299638, 2020). "Another OGT inhibitor, OSMI-1, developed via high-throughput screening, inhibits protein O-GlcNAcylation and decreases tumor volume." (PMID 33194731, 2020). "Immunohistochemistry of OGP, OGT, and OGA in tumor tissues from patients revealed that CCA tissues had increased expression of OGPs which resulted from the increase of OGT and decrease of OGA expression." (PMID 30444036, 2019). "We demonstrated that OGT was highly expressed in both DLBCL cell lines and primary tumor cells from patients." (PMID 27716624, 2016). "To assess the importance of the HBP in cellular growth and survival of DLBCL cells, we analyzed OGT protein and mRNA expression in DLBCL cell lines, primary DLBCL tumor cells, and normal human B-lymphocytes." (PMID 27716624, 2016).
tumor (continued). "As a result, increased levels of OGT and MGEA5 mRNA were found to be related to larger tumor size, nodal metastases, higher grade and tumor behavior according to the TFG scale, as well as incidence of disease recurrences." (PMID 25315705, 2015). "As a result, an increased level of OGT and MGEA5 mRNA was related to larger tumor size, nodal metastases, higher grade and tumor behavior according to TFG scale, as well as incidence of disease recurrence (p < 0.05)." (PMID 25315705, 2015). "Many authors have reported that the levels of O-GlcNAc and the protein expression of OGT and OGA are aberrant in different models, including cell lines, murine models, and human tumor samples." (PMID 24918087, 2014). "Moreover, an additional study of 94 patient tumor samples, which when stratified by level of OGT expression, indicated that disease-free survival 5 years post-treatment was higher in patients with low OGT expression profile compared to patients with increased OGT expression." (PMID 23964270, 2013). "Key tool compounds include OGT inhibitors (e.g., OSMI‐1, OSMI‐4) and OGA inhibitors (e.g., Thiamet‐G, MK‐8719), which have provided proof‐of‐concept that pharmacologically modulating O‐GlcNAcylation can alter tumour progression and autophagic flux." (PMID 41540817, 2026). "For example, in prostate cancer, OSMI effectively inhibits OGT‐mediated super‐enhancer‐dependent gene expression and the function of KIF1A protein, which drives neuroendocrine differentiation, thereby significantly suppressing tumor cell proliferation." (PMID 41394960, 2025). "Next, to determine whether this effect is specific for OGT knockout, we performed this experiment in vivo using MC38 tumor-bearing rescue model." (PMID 38168435, 2024). "Additionally, transient expression of wild-type OGT increases PKM2 O-GlcNAcylation, suppresses pyruvate kinase activity in HeLa cells, stimulates aerobic glycolysis, and promotes tumor growth." (PMID 39285476, 2024). "Since O-GlcNAcylation is more involved in regulating the expression of oncogenes, precisely targeting OGT/OGA and HBP flux may have greater anti-tumor efficacy." (PMID 38786029, 2024). "However, the mutual regulation between OGT and CARM1 during tumor progression needs to be further studied." (PMID 39715739, 2024). "The higher O-GlcNAcylation and OGT levels observed in GBM11, cells originated from a tumor recurrence process, might indicate their roles in tumorigenesis." (PMID 37835434, 2023). "As a result, OGT and OGA play a pivotal role in tumor progression and prognosis." (PMID 35795059, 2022). "Interestingly, higher OGT and OGA expression levels were observed in tumor samples and cell lines from hematological malignancies compared with those in other solid tumors." (PMID 36104770, 2022). "Besides intracellular signaling proteins, oncogenic signals from tumor microenvironment and virus oncoproteins can regulate O-GlcNAcylation through HBP enzymes and OGT/OGA." (PMID 35201498, 2021). "Factors in tumor microenvironment can also regulate HBP enzymes and OGT/OGA." (PMID 35201498, 2021). "In addition, the results of RT-qPCR and Western blot assay suggested that the expression of miR-181d, OGT, and NRF2 remained un-altered in mouse tumor tissues." (PMID 34876558, 2021).
tumor (continued). "Although no apparent inhibition of tumor growth was observed by OGT suppression alone or proteasome inhibitor treatment alone in a lung cancer xenograft model, the combination of these two significantly reduced tumor growth." (PMID 33535386, 2021). "When fold changes in the tumor volume on days 3 and 6 against the one on day 0 were calculated, significant suppressive effects of bortezomib were also apparent for the OGT knockdown cells but not for the control cells." (PMID 29941490, 2018). "Notably, treatment of tumor cells with PI3K and mTOR inhibitors led to decreased protein expression of OGT and overall lower levels of O-GlcNAcylation." (PMID 27703839, 2016). "Upregulation of OGT and USP7 has been reported in a number of tumor types." (PMID 26678539, 2015). "Similar to EC, downregulation of OGT in U-87 MG cells by RNAi interference did not inhibit cell viability, indicating that also in tumor cells OGT is a good marker for miR-7 delivery but not for miR-7 efficacy." (PMID 25149532, 2014). "Translational efforts must prioritise the development of highly specific OGT/OGA inhibitors or allosteric modulators and rigorously validate their efficacy – particularly in rational combination regimens – within preclinical models that recapitulate human tumour heterogeneity and therapy resistance." (PMID 41540817, 2026). "To specifically investigate the role of YAP O‐GlcNAcylation in promoting tumor growth in vivo in obese mice, we injected HFD‐fed obese mice with either 4T1 cells (BALB/c mice) or MDA‐MB‐231 cells (nude mice) and treated them with a 5 mg kg−1 OGT inhibitor twice weekly." (PMID 39868848, 2025). "Moreover, OGT inhibits the degradation of HIF-2α by the ubiquitin–proteasome system, upregulates the expression of HIF-2α and its downstream target genes, and promotes tumor progression." (PMID 40852041, 2025). "Finally, studies have revealed that SET domain‐containing protein 5 in CRC upregulates the expression of CSC markers such as ESRRB, CD133, and KLF4 by facilitating OGT‐mediated O‐GlcNAcylation of RNAP II, endowing tumor cells with stem‐like properties—a process dependent on O‐GlcNAcylation." (PMID 41394960, 2025). "However, in our models, shRNA-mediated downregulation of GFPT, but not OGT, leads to a significant decrease in tumor growth and lung metastasis in vivo." (PMID 38732103, 2024). "Different tumour types exhibit varying degrees of dependence on OGT, suggesting that a single inhibitor may be effective in some tumours but not in others." (PMID 39358921, 2024). "This protein modification is catalyzed by an enzyme called O-GlcNAc transferase (OGT), which uses the final product of the Hexosamine Biosynthetic Pathway (HBP) to connect altered nutrient availability to changes in cellular signaling that contribute to multiple aspects of tumor progression." (PMID 37838167, 2023). "Hence, in pancreatic cells, the aberrant OGT interaction and O-GlcNAcylation of YAP promote its dephosphorylation, nuclear localization, and transcriptional activity, fueling Hippo signaling and tumor growth." (PMID 36291918, 2022). "This study also investigates whether OGT and MGEA5 transcripts may affect tumor behavior." (PMID 25315705, 2015). "Therefore, increased MLL5 protein via upregulation of OGT and USP7 in tumor cells may contribute to altered cell proliferation and malignant transformation." (PMID 26678539, 2015). "Interestingly, this protection appears to be specific to tumor cells, because reducing O-GlcNAcylation by OGT knockdown of non-transformed HPDE cells did not trigger apoptosis." (PMID 24918087, 2014). "Tumor size was not correlated with OGT expression (P = 0.78)." (PMID 23554759, 2012). "Because even pharmacological short-term inhibition of glycolysis- and OGT-activity influenced IFNγ production and STAT1 phosphorylation, we propose that this mechanism equips Th1 cells to adapt dynamically to their environment; this could have important consequences for anti-tumor immunity." (PMID 41184108, 2026).
tumor (continued). "In this research, we found that MN could facilitate the binding of OGT-570aa to FOXC1, thus reducing the biogenesis of alanine and asparagine, inducing ferroptosis, and inhibiting tumorigenesis and aggressiveness, which indicates its potential application as an inhibitor of tumor progression." (PMID 40416363, 2025). "Accordingly, BrdU incorporation and cell accounting analysis in tumor cells indicated that hypoxia slightly suppressed the proportion of divided cells, which was aggravated by PFKFB3 or OGT depletion, but without an additional effect when both were depleted." (PMID 32060258, 2020). "Meanwhile, immunoprecipitation analysis of tumor tissues, with WT PFKFB3 but not PFKFB3 S172A, showed the PFKFB3-S172 phosphorylation and PFKFB3-G3BP2 interaction were enhanced by OGT depletion." (PMID 32060258, 2020). "Spatial proteomics further indicates that PTMs are patterned rather than randomly dispersed within the tumor microenvironment: hypoxic niches exhibit elevated PAD4 and O-GlcNAc transferase (OGT) activity, forming localized PTM “hotspots” that coincide with immune-exclusion zones in PDAC." (PMID 41228299, 2025). "We observed that both the CD36 and OGT levels could patients with a higher pStage (stages III and IV), deeper tumor invasion (T3 and T4) and more positive lymph nodes (>5), while the combination of the CD36 and OGT levels showed a high overall accuracy." (PMID 31410220, 2019). "Unfortunately, no data concerning the relationship of OGT and/or OGA (MGEA5) with the presence of an invasive tumor phenotype in malignant head and neck tumors could be found in the literature." (PMID 25315705, 2015).
neurodegenerative disease (12 papers, 2017 to 2026). A disorder of the central nervous system characterized by gradual and progressive loss of neural tissue and neurologic function. "In C. elegans, loss of ogt-1 (homolog of human OGT) partly elevates autophagy, thus alleviating proteotoxicity associated with neurodegenerative diseases." (PMID 35931119, 2022). "Deletion of OGT is lethal and deficiencies in OGT activity are associated with neurodegenerative diseases and gut inflammation." (PMID 30619781, 2018). "The extent of this modification has sparked interest in the medical community to explore OGA and OGT as therapeutic targets, particularly in degenerative diseases." (PMID 33669256, 2021). "Inhibition of O-GlcNAcase (OGA), the enzyme responsible for removing protein O-GlcNAcylation, has been explored as a target for modulating brain O-GlcNAc homeostasis in neurodegenerative diseases and may also be a target for OGT-CDG." (PMID 42209020, 2026). "By enhancing OGT expression independently of O-GlcNAc feedback, these approaches aim to restore proteostasis and improve resilience to neurodegeneration, offering a novel therapeutic approach for aging-related neurodegenerative diseases." (PMID 41629214, 2026). "O-GlcNAc-modified proteins were detected in nerve terminals, and abundant OGT activity was detected in nerve synaptosomes, indicating that O-GlcNAc could play a role in neuronal function and neurodegenerative disease." (PMID 28584052, 2017). "Therefore, we predict that targeting OGT inhibition might help to defend against a wide variety of neurodegenerative diseases by stimulating autophagy." (PMID 31827688, 2019). "We found that each animal has its unique value for OGT, OGA, OGA activity, mitochondrial activities and parameters of autophagy proteins and proteins involved in neurodegenerative diseases." (PMID 35248135, 2022). "Conversely, OGT or GFAT agonists could be combined with OGA inhibitors to increase O‐GlcNAcylation levels, offering new approaches for neurodegenerative diseases and some autoimmune disorders." (PMID 41394960, 2025).